MTOR (mechanistic target of rapamycin kinase)
Diseases named in the same sentence as MTOR in open-access papers (continued):
Sharing a sentence is not in itself a finding about the gene and the disease.
tumor (continued). "The signaling pathway of the mechanistic target of rapamycin (mTOR) is one of the most important signaling network downstream of the oncogenic receptor tyrosine kinases (RTKs), which participate in tumor growth, metastasis and therapy evasion." (PMID 32923403, 2020). "The fact that mTOR inhibition can promote tumor cell growth in a primary nutrient-poor, but protein-rich, microenvironment has been put forward as an explanation for the lack of clinical success." (PMID 32101748, 2020). "Its oncogenic role relies on the potential activation of downstream targets PI3K/AKT/mTOR, and deactivation of the upstream tumour suppressor PTEN." (PMID 32704174, 2020). "As early as 1984, the first generation of mTOR inhibitor, rapamycin, was tried for tumor treatment, and subsequent reports suggested that the combined use of rapamycin and other drugs had great antitumor effect." (PMID 32041519, 2020). "Monotherapy such as LY3023414 targets PI3K and mTOR simultaneously and inhibits the compensatory pathway, which obstructs tumor growth and survival." (PMID 32578154, 2020). "In another aspect, for the γδ T cells, tumor-intrinsic mTOR inhibition promotes the epidermal recruitment of CXCL10-mediated CXCR3+ γδ T-cell and shows anti-tumor effect." (PMID 32483450, 2020). "Abnormally elevated mTOR expression promotes tumor proliferation and metastasis in many human malignancies." (PMID 32256500, 2020). "Clinical trials which are focused on combination therapies for HTC include targeting the immunological landscape of HTC along with tumor angiogenesis, tyrosine kinase receptors, and overactive mTOR signaling." (PMID 32605113, 2020). "In fact, metabolic reprogramming in GBM is a consequence of the PI3K/Akt/mTOR signaling. mTOR is a central pathway regulating the tumor microenvironment and its activation promotes GBM growth." (PMID 32817393, 2020). "In the restoration assay, activation of the Akt/mTOR signaling by 740Y-P or pcDNA-Akt plasmid abolished the anti-tumor effect of deoxyshikonin in AML cells." (PMID 32850379, 2020). "Growing evidence suggests that RPS6KB1 and RPS6, two key proteins in the mTOR pathway, as crucial drivers of tumor onset, progression and BRAFi resistance." (PMID 33082316, 2020). "Both IGF-1R inhibitor and mTOR inhibitor treatment significantly reduced the tumor growth in ES xenografts through inhibition of IGF-1R/PI3K/AKT/mTOR, and other signaling pathways, including MEK1/2, JAK/STAT3, TGF-β, and G-protein coupled receptors." (PMID 32754598, 2020). "The TSC1-TSC2 protein complex is required for the suppression of mammalian target of rapamycin (mTOR) activity and therefore referred to as a tumor suppressor." (PMID 32381101, 2020). "The authors also showed that tumour growth was inhibited, the number of tumour-infiltrating T cells was increased and the density of Treg cells decreased with the combined treatment of mTOR inhibition and anti-PD1 agents." (PMID 32327707, 2020). "The mTOR-TF axis functionally contributes to an unfavorable tumor microenvironment relevant for disease progression and therapy resistance." (PMID 32923403, 2020). "For instance, miR-199a-3p inhibits tumor growth in an animal model of HCC by modulating the mTOR pathway." (PMID 32670881, 2020). "The mTOR or AKT suppression were also beneficial in inhibiting tumor cells’ proliferation and restoring cisplatin sensitivity due to miR-222 up regulation." (PMID 33183321, 2020). "The obtained results from the pathway enrichment analysis of the identified DEGs underlined the importance of the crosstalk between tumor cells and extracellular matrix, including integrin and PI3K-Akt-mTOR signaling pathways, in PDAC pathogenesis." (PMID 33194391, 2020). "The role of the AKT/mTOR pathway has been well studied in cell proliferation, autophagy regulation, and tumor development." (PMID 32878322, 2020). "Recent evidence has reported that the mTOR signaling pathway also plays a key role in tumor motility, invasion, and metastasis." (PMID 33293473, 2020).
tumor (continued). "We demonstrate that the pro‐tumourigenic role of TAM‐MG in GBM is mediated by mTOR, as reduced tumour growth and increased survival were observed upon genetic silencing of the pathway in these cells in GL261 allografts." (PMID 32567735, 2020). "Several preclinical studies combining mTOR inhibition with mitochondrial inhibitors, such as metformin, showed synergistic inhibition of tumour growth in pancreatic and breast cancer." (PMID 33092283, 2020). "By enhancing anabolic processes, the mTOR pathway plays an important role in the regulation of cell proliferation, growth, and survival to fulfill the bioenergetic demands of tumor cells in response to environmental signals and intracellular conditions." (PMID 32709151, 2020). "The importance of mTOR signaling in tumor cells has been extensively studied, but relatively little is known about mTOR signaling in tumor blood vessels." (PMID 32759497, 2020). "MCF7LR tumor-bearing mice were treated with letrozole, Z-endoxifen (50 mg/kg), fulvestrant, exemestane, or exemestane plus everolimus (an mTOR inhibitor) and their effects on tumor growth assessed in vivo." (PMID 32430040, 2020). "Comparing to the control groups, p-AKT and p-mTOR levels were reduced in WTX-overexpressing tumours but increased in WTX knockdown tumours." (PMID 33032635, 2020). "Monotherapy with PI3K/mTOR dual inhibitors is of interest in tumor types with a particularly high incidence of aberrant PI3K pathway activation by PIK3CA mutations, amplification, or loss of PTEN tumor suppressor protein." (PMID 32578154, 2020). "Previous studies have shown that the newly discovered drug LY3023414 inhibits the PI3K/mTOR/DNA dependent protein kinase (DNA-PK) pathway in vitro tumor cells and has anti-tumor proliferation activity." (PMID 32175074, 2020). "mTOR is a serine/threonine protein kinase, whose aberrant activation is very prevalent in malignant cells, contributing to tumor formation and progression." (PMID 32626538, 2020). "Specifically, signaling through PDL1 was found to directly upregulate glycolysis in tumor cells through activating the AKT/mTOR pathway, leading to enhanced glucose uptake and lactate production and the expansion and survival of these tumor cells." (PMID 33178201, 2020). "PI3K/AKT/mTOR kinases are important regulators of multiple cellular processes, including metabolism, proliferation, protein synthesis, programmed cell death, tumor invasion and angiogenesis." (PMID 32218702, 2020). "Of note, the analyzed tumor lysates from the Rapalink-1-treated mice group showed that the effects on mTOR activation and lipid metabolism regulation were heterogeneous." (PMID 32656088, 2020). "mTOR, the mammalian target of rapamycin or the mechanistic target of rapamycin, plays a role in tumor cell proliferation and angiogenesis." (PMID 32489466, 2020). "The angiogenesis required for tumor growth is inhibited by mTOR inhibitor use, leading to a slowing of the proliferation of malignant cells." (PMID 32605413, 2020). "In a previous study, the tumor associated macrophages were shown to accelerate the endocrine resistance of MCF-7 cells treated with TAM, due to activation of the PI3K/Akt/mTOR signaling pathway." (PMID 32722075, 2020). "In vivo, TM also caused tumor cell apoptosis, blunted PI3K/Akt/mTOR signaling and decreased S6 phosphorylation." (PMID 32085796, 2020). "We identified that high WNT4 expression is associated with similar mTOR pathway activation in ILC and serous ovarian cancer tumors, suggesting that WNT4 signaling is active in multiple tumor types." (PMID 33053661, 2020). "There are also studies that show that macrophages play a role in tumour growth by activating tumour AKT/mTOR pathways." (PMID 32226513, 2020).
tumor (continued). "In addition, our findings that mTOR signalling-activity-related markers (both p-S6 and Rictor expression), as part of metabolic plasticity evaluation, help to predict prognosis subtype independently underline the importance of metabolic rewiring mechanisms in tumour cells and tissues, as well." (PMID 32899149, 2020). "TMEM127 is a negative regulator of the mTOR pathway and a tumor suppressor located on chromosome 2q1130." (PMID 33037176, 2020). "Phosphatidylinositol 3-kinase (PI3K)/protein kinase B (AKT)/mammalian target of rapamycin (mTOR) pathway is necessary in many neoplasms." (PMID 33066449, 2020). "RICTOR is a scaffold protein that activates mTORC2 complex constituting mammalian Target of Rapamycin or mTOR, an intracellular serine/threonine kinase involved in intracellular cell survival, tumor growth, and drug resistance." (PMID 32724061, 2020). "Another autophagy-related pathway is the phosphatidylinositol-3-kinase (PI3K)/Akt/mTOR signaling pathway, which is involved in cell growth and proliferation and functions as a tumor promoter." (PMID 32545395, 2020). "Inhibition of the PI3K/Akt pathway further limits the target of rapamycin (TOR) complexes 1 (mTORC1) and prevents activation of the mTOR pathway, which increases protein synthesis in tumor cells." (PMID 32370764, 2020). "We separated tumours into those with the signature (group 1: positive mTOR and microglia enrichment, displayed in orange) and those without the signature (group 2: displayed in green)." (PMID 32567735, 2020). "In this study, we demonstrated that additional inhibition of the PI3K/AKT/mTOR pathway led to further suppression of tumor growth." (PMID 32927828, 2020). "Specific chemical inhibitors of receptor tyrosine kinase/Class I PI3K/AKT/mTOR pathway have been shown to be effective anti-tumor therapies." (PMID 33239065, 2020). "Several preclinical experiments have shown that the single or combined use of mTOR inhibitors can significantly inhibit tumor growth, increase cell sensitivity to TKIs, and even reverse drug resistance." (PMID 32041519, 2020). "Upregulation of mTOR signaling can promote tumor growth and progression through diverse mechanisms including the promotion of growth factor signaling, angiogenesis, glycolytic pathways, lipid metabolism, cell migration, and suppression of autophagy." (PMID 32131492, 2020). "As the mTOR pathway is upregulated in tumour cells, mTOR inhibitors can reduce tumour growth by inhibiting angiogenesis and inducing the apoptosis of tumour cells." (PMID 33053849, 2020). "Tumor cells rewire their bioenergetic and biosynthetic pathways to support cell growth and survival, in which mTOR can play a key role." (PMID 32709151, 2020). "The phosphatidylinositol 3-kinase (PI3K)/protein kinase B (AKT)/mammalian target of rapamycin (mTOR) pathway is a critical survival pathway for cell proliferation, apoptosis, autophagy and translation in neoplasms." (PMID 33066449, 2020). "Collectively, the Akt/mTOR signaling pathway is involved in the tumor-promoting effect of PRDX2 in NSCLC cells." (PMID 32337219, 2020). "BHD is caused by germline mutation in the folliculin (FLCN) gene on chromosome 17p11.2, a tumor suppressor gene known to be involved in the signaling of mammalian target of rapamycin (mTOR)." (PMID 32631372, 2020). "Taken together, mTOR is not only involved in tumor progression, but also influences the biological environment of immune cells." (PMID 32483450, 2020). "Our previous study identified compounds which inhibit mitochondrial membrane potential, inhibit mTOR, and kill tumor cells upon glucose starvation in culture." (PMID 32033217, 2020). "The PI3K-Akt-mTOR signaling pathway was first found in tumor cells and was shown to regulate numerous cell functions." (PMID 32620113, 2020). "By inhibiting its target mTOR (PI3K/AKT/mTOR pathway), miR-7 induces apoptosis and suppresses tumor growth in in vivo experiments." (PMID 33142817, 2020).
tumor (continued). "A number of studies have shown that a variety of new mTOR inhibitors show high anti-tumor activity in clinical studies, and the use of mTOR inhibitors in combination with other anti-tumor drugs has a significant effect." (PMID 32175074, 2020). "BIA has emerged as a potential candidate as an antagonist regulating TMBIM6-mTORC2 interaction and its related tumor growth even in cases that are resistant to mTOR inhibitors." (PMID 32782388, 2020). "Autophagy induction by 2DG/DCA was restored upon mTOR inhibition, indicating a profound mTOR-dependent defect in the autophagy response of PI3Ki-resistant tumor cells." (PMID 32943635, 2020). "Down-regulation of PI3K, AKT1 and PI3K/mTOR reduced the self-renewal and survival of BCSCs in vitro and their tumor initiation and self-renewal ability in vivo." (PMID 33584277, 2020). "mTOR renders the metabolic program switch to aerobic glycolysis in tumor cells by activating HIF1α, a positive regulator of many glycolytic genes 51,52." (PMID 32626538, 2020). "To summarize, the present study identified that expression of miR-20b and miR-451a are deregulated in vitro and in vivo and have a tumor suppressive role in GC through regulation of the PI3K/AKT/mTOR signaling pathway." (PMID 32013265, 2020). "Accumulating research evidence, not limited to PI3K, AKT, and mTOR, has also unveiled tumor-promoting function of important molecules that manipulate activation of the PI3K/AKT/mTOR pathway." (PMID 33028805, 2020). "In general, the mTOR pathway, which is often activated in tumors, promotes tumor growth by regulating the differentiation and function of immune cells." (PMID 32175074, 2020). "On the other hand, we blocked the mTOR signaling pathway to potentially target tumor bone colony formations and spine metastasis growth, as the last step in metastasis bone formation." (PMID 32140451, 2020). "The outcome of chemokines-mediated immune cells chemotaxis interacts with the cue of mammalian target of rapamycin (mTOR) in the tumor microenvironment (TME)." (PMID 32483450, 2020). "LB-100, a small molecular inhibitor of protein phosphatase 2A (PP2A), has been shown to enhance T cell anti-tumor activity through activation of the mTOR signaling pathway." (PMID 31935881, 2020). "mTOR is an important signaling pathway for glutamine metabolism and is differentially regulated by glutamine concentration of tumor cells." (PMID 32670883, 2020). "Treatment with antidiabetic drug, metformin, and mTOR inhibitor, everolimus, has shown to reduce tumor growth and are being tested in clinical trials." (PMID 33505918, 2020). "Further, the Patient 1 tumor, its derivative cell lines and UW-CSCC2 all harbored copy number amplifications in genes of the PI3K/mTOR signaling pathway, as well as mutations in AKT3, supporting this as a key targetable pathway in metastatic cSCC." (PMID 33333825, 2020). "Phosphatidylinositol-3-kinase/AKT/mTOR signaling pathway is considered as the main regulator of tumor." (PMID 32082999, 2020). "All these results suggest that baicalein and baicalin down-regulate the mTOR-HIFα signaling in tumor cells." (PMID 32984331, 2020). "By suppressing Akt/mTOR signaling pathway, miR-708 acts as an anti-tumor agent to inhibit ZEB1, leading to the suppressing EMT mechanism." (PMID 32664703, 2020). "The purpose of this review is to introduce the role of mTOR signaling pathway on apoptosis, autophagy, growth, and metabolism of tumor cells, and to introduce the research progress of mTOR inhibitors in the tumor field." (PMID 32175074, 2020). "Research has shown that isolated mTOR or PI3K inhibition can radiosensitise tumours in vitro and in vivo." (PMID 32443649, 2020).
tumor (continued). "Phosphatidylinositol-3 kinase (PI3K)/Akt/mammalian target of rapamycin (mTOR) pathway represents another critical signaling axis which supports tumor growth, also through stimulation of protein synthesis and angiogenesis." (PMID 33379141, 2020). "Autophagy can be regulated by many signaling pathways including PI3K/AKT/mTOR pathways, which is crucial in tumor initiation and progression." (PMID 32655130, 2020). "For example, FBXW7 acts as a tumor suppressor by targeting mTOR, HIF-1α, c-Myc and SREBP1 for degradation." (PMID 33004065, 2020). "In vitro, by decreasing the expression and nuclear localization of p-AKTSer473, Ferulin C (20μM) significantly inhibited the expression and phosphorylation of AKT and its downstream member mTOR, thus inducing autophagy of tumor cells." (PMID 33344242, 2020). "In order to evaluate the underlying mechanism of action of the dual mTOR inhibitor PP242, the LS174T xenograft mouse model was treated with PP242 for 3 weeks, and plasma and tumor samples were analyzed via metabolomics and lipidomics approaches." (PMID 33067464, 2020). "Discontinuation of mTOR inhibitors treatment leads to tumor regrowth (such as kidney AML, SEGA, skin lesions, and cardiac rhabdomyoma) in the majority of patients." (PMID 32887218, 2020). "The decreased LGR5, β-catenin, mTOR, and IL-6 levels, and increased miR-142-3p level in tumor samples collected from mice that received MSI-N1014, support our proposed anti-CRC mechanism of action." (PMID 32560222, 2020). "An extensive in silico and in vitro analysis comparing normal versus tumor tissue in more than 3700 cases revealed that up-regulated hsa-miR-375 accelerated cell proliferation by regulating the PI3K/Akt/mTOR pathway." (PMID 33255991, 2020). "As a result of activation of the PI3K/AKT/mTOR signaling pathway, miR-361-5p inhibited autophagy and increased the sensitivity of tumor cells to chemotherapy." (PMID 33142817, 2020). "Taken together, various CXCL12-mediated T cells and tumor cells chemotaxis were connected with mTOR signaling, but mTOR interventional therapy plays a pros or cons role in different conditions of TME, and it is unclear." (PMID 32483450, 2020). "Tumor immunotherapy is a hot research topic in recent years, and a variety of evidence shows that mTOR pathway, which is often abnormally activated in tumors, can regulate the differentiation and function of immune cells." (PMID 32175074, 2020). "We further noticed that the expression of Akt/mTOR pathway in tumor tissues were downregulated in a xenograft nude mouse mode." (PMID 33116125, 2020). "We proceeded to evaluate the efficacy of metabolic compounds for targeting tumor cells with mTOR-dependent drug resistance in vivo." (PMID 32943635, 2020). "The inactivation or downregulation of nuclear receptor 4A1 (NR4A1) downregulates TXNDC5, isocitrate dehydrogenase 1, and the mTOR (mammalian target of rapamycin) pathway, further promoting ROS generation, inducing apoptosis, and inhibiting tumor growth." (PMID 33228209, 2020). "Whilst functional ontology of many proteome differences was conserved between tumor clones (e.g. mTOR), heterogeneity still exists in redundant pathways of epigenetic regulation and chromatin remodeling (e.g. KMTs and KATs)." (PMID 33087703, 2020). "Virtually, the PI3K/AKT/mTOR signaling was crucial to modify tumor development and chemo-sensitivity." (PMID 33336063, 2020). "It is well known that rapamycin, the inhibitor of mTOR, has been widely used in the clinic for tumor treatment." (PMID 33204686, 2020). "Specifically, we focus on the involvement of mTOR in chemokine-mediated immune related cells in the balance between tumor immunity and malignancy." (PMID 32483450, 2020). "A significant decrease in miR-7, which induces autophagy by targeting mTOR, was observed in tumour tissue compared to normal tissue suggesting its potential antitumor role in HCC." (PMID 33362215, 2020).